Y_RNA (Y RNA )
Gene: Miscellaneous RNA gene on chromosome 15 (33,722,492 to 33,722,596, forward strand). Ensembl gene ENSG00000200008.
Homologues: Orthologues: chimpanzee Y_RNA (99% identical), macaque Y_RNA (92% identical). Paralogues in human: Y_RNA (86% identical), Y_RNA (85% identical), Y_RNA (84% identical), RNY3 (83% identical), RNY3P16 (83% identical), Y_RNA (83% identical), Y_RNA (82% identical), Y_RNA (81% identical), RNY3P1 (80% identical), Y_RNA (80% identical), RNY3P14 (79% identical), Y_RNA (79% identical), and 94 more.